NRG4 (neuregulin 4)
Description:
Low affinity ligand for the ERBB4 tyrosine kinase receptor. Concomitantly recruits ERBB1 and ERBB2 coreceptors, resulting in ligand-stimulated tyrosine phosphorylation and activation of the ERBB receptors. Does not bind to the ERBB1, ERBB2 and ERBB3 receptors (By similarity).
Synonyms: HRG4
Tractability: Antibody: its Gene Ontology location is reachable by antibodies, with high confidence; UniProt places it where antibodies can reach, with medium confidence; UniProt predicts a signal peptide or a membrane-spanning region.
Gene: Protein-coding gene on chromosome 15 (75,935,969 to 76,059,795, reverse strand). Ensembl gene ENSG00000169752.
Subcellular location: Cell membrane (Pro-neuregulin-4, membrane-bound isoform); Secreted (Neuregulin-4)
Pathways (Reactome):
Signal Transduction: Downregulation of ERBB2 signaling; ERBB2 Activates PTK6 Signaling; ERBB2 Regulates Cell Motility; GRB2 events in ERBB2 signaling; Nuclear signaling by ERBB4; PI3K events in ERBB2 signaling; PI3K events in ERBB4 signaling; PI5P, PP2A and IER3 Regulate PI3K/AKT Signaling; PIP3 activates AKT signaling; RAF/MAP kinase cascade; SHC1 events in ERBB2 signaling; SHC1 events in ERBB4 signaling; Signaling by ERBB2; Signaling by ERBB4
Disease: Constitutive Signaling by Aberrant PI3K in Cancer; Signaling by ERBB2 KD Mutants; Signaling by ERBB2 TMD/JMD mutants
Gene Ontology:
Molecular function: protein binding; receptor ligand activity
Biological process: ERBB4-ERBB4 signaling pathway
Cellular component: extracellular region; plasma membrane
Homologues: Orthologues: chimpanzee NRG4 (96% identical), macaque NRG4 (90% identical), pig NRG4 (86% identical), mouse Nrg4 (75% identical), rat Nrg4 (65% identical), guinea pig NRG4 (63% identical), rabbit NRG4 (57% identical). Paralogues in human: NRG3 (28% identical), NRG1 (25% identical), NRG2 (23% identical).
Diseases named in the same sentence as NRG4 in open-access papers:
NRG4 is named in the same sentence as 86 diseases in open-access papers, as found by Europe PMC text mining. Sharing a sentence is not in itself a finding about the gene and the disease. The quoted sentences say what the papers report.
Obesity (57 papers, 2016 to 2025). Accumulation of substantial excess body fat. "Reduced NRG4 expression in adipose tissue and plasma levels has been associated with obesity and insulin resistance." (PMID 40433407, 2025). "Nrg4 has been associated with several metabolic disorders, including insulin resistance, obesity, nonalcoholic fatty liver disease (NAFLD), and diabetes." (PMID 40283014, 2025). "Genetic loss of Nrg4 has been associated with impaired BAT vascularization, obesity, and metabolic dysfunction in chow diet-fed mice, supporting the critical role of Nrg4 in regulating adipose tissue vascular and metabolic functions." (PMID 39335642, 2024). "Since obesity is characterized by a chronic inflammatory response, it has been demonstrated that low Nrg4 levels were negatively associated with inflammatory markers, such as hs-CRP, TNF-α, IL-6, and MCP-1 in conditions of MetS." (PMID 39162358, 2024). "This systemic review provides a crucial analysis of evidence regarding the role of Nrg4 as a potential risk factor and/or biomarker for obesity, GDM, T2DM, NAFLD, and CVD." (PMID 39162358, 2024). "By whole-exome sequencing and exome genotyping of obesity, a recent study has identified two rare missense mutations in NRG4: Nrg4 E47Q and Nrg4 R44H." (PMID 39872218, 2024). "Previous studies reported an inverse association between adipose tissue expression of Nrg4 and the circulating levels of this protein with insulin resistance in humans and in mouse models of obesity and type 2 diabetes." (PMID 39519269, 2024). "NRG4 expression is reduced in adipose tissue from obese mice, and lower plasma NRG4 levels are associated with obesity, insulin resistance, and NAFLD in humans." (PMID 38015639, 2024). "Preclinical evidence showed that Nrg4 overexpression prevented high-fat diet-induced obesity, insulin resistance, and hepatic lipogenesis in mice, while Nrg4 deficiency exacerbated hepatic steatosis and insulin resistance." (PMID 39162358, 2024). "Neuregulin-4 associated especially with insulin resistance, obesity and obesity-related metabolic dysregulations is a protective factor." (PMID 37373801, 2023). "Previous studies have also found that high-fat-fed Nrg-4 knockout mice have higher plasma TG concentrations, higher FPG and plasma insulin levels, suggesting that Nrg-4 deficiency can lead to glucose tolerance after diet-induced obesity." (PMID 36915073, 2023). "It has been reported that decreased NRG4 levels are closely associated with type 2 diabetes, obesity, hyperglycemia, oxidative stress and inflammation." (PMID 36983737, 2023). "To elucidate the causes of central Nrg4‐induced reduction in dietary obesity, we measured food intake and energy expenditure in these mice." (PMID 37060105, 2023). "Circulating Nrg4 levels were negatively associated with subclinical atherosclerosis in adults with obesity." (PMID 36703934, 2022). "The adipokine Nrg4 plays an important role in regulating systemic energy metabolism and is involved in the pathogenesis of obesity-associated disorders, including DM and nonalcoholic fatty liver disease." (PMID 36221104, 2022). "In humans, the association between NRG4 and obesity-associated insulin resistance and liver steatosis is less clear and controversial." (PMID 36187779, 2022). "Another study including 123 children with obesity found that circulating Nrg4 levels were negatively and significantly associated with NAFLD and other metabolic-related parameters." (PMID 36703934, 2022). "Neuregulin 4 (NRG4) has been described to improve metabolic disturbances linked to obesity status in rodent models." (PMID 36187779, 2022). "A recent study identified two rare missense mutations in NRG4, Nrg4 E47Q, and Nrg4 R44H, by whole-exome sequencing of 224 subjects with obesity and exome genotyping of 2,388 participants from the Shanghai Obesity Study." (PMID 36703934, 2022).
Obesity (continued). "Our results suggest that HIIT and CRT protocols have greater effects than MICT protocol on Nrg4 levels, metabolic and cardiovascular risk factors, and body composition variables in men with obesity." (PMID 35197860, 2021). "This study examined the effects of 12 weeks of three different exercise training protocols on Nrg4 levels, cardiometabolic risk factors, and body composition parameters in men with obesity." (PMID 35197860, 2021). "Plasma NRG4 levels have also been shown to be inversely related to the risk of obesity, metabolic syndrome and type 2 diabetes." (PMID 32541662, 2020). "Taken together, these researches established the therapeutic potential of Nrg4 for treatment of obesity and associated disorders such as diabetes mellitus (DM)." (PMID 31815951, 2019). "Further, adipose tissue inflammation is likely a driving force in obesity-associated decrease of Nrg4 expression in adipose tissue." (PMID 28752050, 2017). "Nrg4 was identified as a brown fat-enriched endocrine factor that improves obesity-associated insulin resistance and hepatic steatosis." (PMID 28752050, 2017). "Nrg4 exerts pleiotropic beneficial effects on energy balance and glucose and lipid metabolism to ameliorate obesity-associated metabolic disorders." (PMID 28752050, 2017). "In this study, we systematically examined the effects of Nrg4 gene transfer on high fat diet-induced obesity and obesity-associated metabolic changes." (PMID 27184920, 2016). "Nrg4 has been identified as being involved in crosstalk between brown fat tissue and obesity-associated disorders." (PMID 27772531, 2016). "Nrg4 is a brown fat-enriched endocrine factor recently been shown to improve obesity-associated disorders, including type 2 diabetes and NAFLD." (PMID 27772531, 2016). "Nrg4 is expressed in adipocytes, the deficiency of which exacerbates diet-induced insulin resistance and obesity in animal models." (PMID 27772531, 2016). "Collectively, these data demonstrated that prolonged Nrg4 gene expression alleviates obesity-associated fatty liver." (PMID 27184920, 2016). "Although the effects of asprosin and Nrg4 are not fully understood, both have been shown to be associated with various chronic diseases; however, further research is needed to confirm their roles in causing obesity in children." (PMID 40283014, 2025). "Reduced levels of Nrg4 are linked to obesity, insulin resistance, diabetes, dyslipidemia, metabolic syndrome, non-alcoholic fatty liver disease, inflammation, oxidative stress, and macrovascular diseases such as coronary artery disease and myocardial infarction." (PMID 40137134, 2025). "Additionally, Nrg4 promotes angiogenesis in adipose tissue, and its deficiency leads to reduced vascularization and the development of obesity even under normocaloric conditions." (PMID 40426925, 2025). "NRG4-deficient mice are susceptible to obesity, insulin resistance, and hepatic steatosis." (PMID 39872218, 2024). "Although Nrg4 had a low cut-off point, both Nrg4 and adiponectin levels were associated with the degree of metabolic disorders, suggesting the potential to predict the occurrence or risk of metabolic disease in children and adolescents with obesity." (PMID 39162358, 2024). "Moreover, current observational studies assessing the correlation between Nrg4 levels, and the risk of developing obesity and metabolic disease are focused on the adult population, with limited data on children and adolescents." (PMID 39162358, 2024). "In adipose tissue, TNF-α may be involved in the regulation of Nrg4 level which may be one of the causes of the reduced Nrg4 expression in obesity with chronic inflammation." (PMID 39162358, 2024). "Nrg4 is closely associated with obesity and preserves diet‐induced metabolic disorders." (PMID 37060105, 2023).
Obesity (continued). "Nrg-4, another novel adipokines, is mainly secreted by brown adipose tissue and is associated with dyslipidemia, IR, inflammation, and oxidative stress, which are involved in the pathogenesis of obesity, diabetes, and metabolic syndrome." (PMID 36915073, 2023). "NRG4 or ErbB4-induced downregulation led to insulin resistance and hepatic steatosis in high-fat diet-fed mice, supporting the importance of NRG4-ErbB4 signalling in the prevention of obesity-associated metabolic disturbances." (PMID 36187779, 2022). "Additionally, circulating NRG4 was significantly associated with insulin resistance indicators, markers of obesity, and hormonal levels." (PMID 35206286, 2022). "Nrg4 levels in men with obesity were significantly increased by 12 weeks of resistance training (conventional, circular, and interval), suggesting that Nrg4 may be involved in exercise-induced weight loss." (PMID 36703934, 2022). "In addition, low plasma levels of Nrg4 in the blood are independently associated with an increased risk of metabolic syndrome in individuals with obesity, and are also negatively correlated with blood glucose levels and body fat mass." (PMID 35197860, 2021). "Consistent with this hypothesis, mice with a global deletion of nrg4 are more prone to develop diet-induced insulin resistance and hepatic steatosis, while fat-specific overexpression of nrg4 protects mice from obesity-associated metabolic dysfunction (Wang." (PMID 32372975, 2020). "For these reasons, the aim of our meta-analysis was to investigate whether circulating Nrg4 levels were associated with DM and clinical indices of diabetes, renal function, metabolic syndrome and obesity in diabetes patients." (PMID 31815951, 2019). "Evidence showed that Nrg4 deficiency in mice and human obesity adipose tissue could aggravate insulin resistance and diet-induced lipid metabolic disorder." (PMID 31815951, 2019). "Our findings suggested circulating Nrg4 may play a role in in the development of DM in cross-sectional studies and circulating Nrg4 might be associated with imbalance in glucose metabolism and obesity." (PMID 31815951, 2019). "Plasma concentrations of Nrg4, a novel adipokine expressed in adipose tissues (especially brown adipose tissue), may be associated with obesity, IR, T2DM, lipid metabolism, inflammation, and atherosclerosis." (PMID 29721105, 2018). "However, the potential roles of circulating Nrg4 in contributing to obesity-associated disorders and the associations of circulating Nrg4 with metabolic risk factors and MetS remain to be elucidated in population-based studies." (PMID 27772531, 2016). "However, the potential roles of circulating Nrg4 in contributing to obesity-associated disorders and the associations of circulating Nrg4 with metabolic risk factors remain to be elucidated in population-based studies." (PMID 27819316, 2016). "Notably, obesity disrupts this process by inducing mitochondrial dysfunction (e.g., reduced oxidative phosphorylation and mtDNA mutations) in transferred organelles, while concurrently suppressing protective adipokines such as Neuregulin-4 (Nrg4)." (PMID 40642747, 2025). "Therefore, it was hypothesised that the systemic pro-inflammatory activity associated with the metabolic syndrome contributes to the obesity-induced downregulation of Nrg4 in BAT and WAT." (PMID 33989346, 2021). "Because Nrg4 transgenic mice exhibited reduced fat mass and elevated energy expenditure, our findings raise the possibility that Nrg4/ErbB4 signaling may be a genetic factor for human obesity and its associated metabolic disorders." (PMID 28752050, 2017). "Larger sample sizes would enhance the reliability of the data and provide a more in-depth investigation into the role of asprosin and Nrg4 in the pathogenesis of obesity." (PMID 40283014, 2025).
Obesity (continued). "We found that anthocyanins, punicalagin, oleanolic acid and NRG4 proved to be critical nodes in the transition from obesity to the healthy state, due to their individual switch-on potential to up-regulate the complex network resulting in beneficial transition." (PMID 40433407, 2025). "Nrg4 exhibits protective properties against the development of obesity, with its expression in adipose tissue significantly reduced in both obese humans and mice." (PMID 40426925, 2025). "By enhancing insulin sensitivity, regulating lipid metabolism, and protecting against cardiac remodeling, NRG4 represents a promising therapeutic target in addressing heart disease, particularly in populations affected by obesity and type 2 diabetes." (PMID 40149686, 2025). "We found that anthocyanins, punicalagin, oleanolic acid, and NRG4 proved to be critical nodes in the transition from obesity to the healthy state, due to their switch-on potential to up-regulate the complex network resulting in a beneficial transition." (PMID 40433407, 2025). "This decrease is associated with the chronic inflammation characteristic of obesity, as demonstrated by in vitro studies showing that pro-inflammatory cytokines such as TNF-α and IL-1β suppress Nrg4 expression." (PMID 40426925, 2025). "In our study, serum Nrg4 levels were found to be significantly higher in children with obesity compared to normal-weight controls." (PMID 40283014, 2025). "Using MMTV-PyMT and 4T1 breast cancer models, we demonstrate that obesity accelerates metastasis, while NRG4, secreted by inguinal white adipose tissue (iWAT), inhibits cancer cell migration and epithelial-mesenchymal transition (EMT)." (PMID 41716632, 2025). "In children with obesity, low serum NRG4 correlates with insulin resistance and MASLD, while elevated NRG4 levels are associated with reduced metabolic risk." (PMID 40580113, 2025). "All of this information explains the higher levels of NRG4 in metabolically healthy people with obesity." (PMID 39008201, 2024). "Our systematic search yielded thirty-one (n = 31) studies reporting the circulating levels of Nrg4 in participants with obesity and MetS (n = 4), NAFLD (n = 4), GDM (n = 7), T2DM (n = 12), and CVD-related disorders (n = 4)." (PMID 39162358, 2024). "Pro-inflammatory factors like tumor necrosis factor α (TNF-α) and IL-1β reduce NRG4 expression in adipocytes, likely contributing to the reduced NRG4 in obesity." (PMID 39872218, 2024). "In conditions associated with insulin resistance, such as obesity and T2DM, the expression of Nrg4 in adipocytes is reduced." (PMID 39335642, 2024). "Different results were found in studies investigating the relationship between metabolic health and NRG4 in individuals with obesity." (PMID 39008201, 2024). "Many studies have demonstrated that the severity of obesity and MetS were closely linked with low circulating levels, whereas increased Nrg4 levels were deemed as a rescue or compensatory response to metabolic dysregulations in simple obesity." (PMID 39162358, 2024). "In a study, low serum NRG4 concentrations were found to be related to insulin resistance (IR), fatty liver disease, as well as obesity in obese children." (PMID 39280566, 2024). "Clinical research indicates that circulating levels of Nrg4 are significantly lower and negatively correlated with BMI and WC in patients with obesity and MetS." (PMID 39162358, 2024). "Our study aims to compare the relationship between the demographic characteristics and the biochemical parameters of the participants and biomarkers (BMP1, NRG4 and ApoA5) thought to be related to obesity." (PMID 39280566, 2024). "Our systematic search yielded four (n = 4) studies specifically reporting on the modulation of Nrg4 in individuals with obesity and MetS." (PMID 39162358, 2024). "The intergroup comparison indicated significant increases in plasma Nrg-4 in the CV group compared to the control group, indicating that CV increased plasma Nrg-4 levels in obesity." (PMID 39036605, 2024).